MIR146B (microRNA 146b)
Synonyms: hsa-mir-146b; MIRN146B; miRNA146B; mir-146b
Gene: MicroRNA gene on chromosome 10 (102,436,512 to 102,436,584, forward strand). Ensembl gene ENSG00000202569.
Gene Ontology:
Biological process: miRNA-mediated post-transcriptional gene silencing
Cellular component: RISC complex
Homologues: Orthologues: chimpanzee ptr-mir-146b (100% identical), macaque mml-mir-146b (99% identical), mouse Mir146b (93% identical), rat Mir146b (92% identical), guinea pig MIR146B (82% identical), dog MIR146B (73% identical), zebrafish mir146a (60% identical).
Diseases named in the same sentence as MIR146B in open-access papers:
MIR146B is named in the same sentence as 14 diseases in open-access papers, as found by Europe PMC text mining. Sharing a sentence is not in itself a finding about the gene and the disease. The quoted sentences say what the papers report.
anaplastic astrocytoma (1 paper, 2018). "Contrarily, the hypermethylation and down-expression of MIR146B were reported in diffuse and anaplastic astrocytomas, gliomas, and breast cancer being the 5-AZA-dC treatment capable to induce the MIR146B expression." (PMID 30454026, 2018).
Anxiety (1 paper, 2022). Intense feelings of nervousness, tension, or panic often arise in response to interpersonal stresses. "Interestingly, Mir146b-/- mice also demonstrated slightly increased anxiety in the OFT and EPM tests." (PMID 35805086, 2022).
depression (1 paper, 2022). "In conclusion, LPS-induced sickness behavior manifested by the rapid decrease in body weight, reduction in locomotor activity and development of depression-like behavior was less severe in Mir146b-/- mice as compared with WT littermates." (PMID 36389659, 2022).
lymph node metastasis (1 paper, 2018). "Hypomethylation and increased expression of MIR146B, as well as decreased target genes expression, were significantly associated with features related to poor prognosis (advanced clinical stage, lymph node metastasis, and extrathyroidal extension) and BRAF mutation." (PMID 30454026, 2018).
melanoma (1 paper, 2018). A malignant, usually aggressive tumor composed of atypical, neoplastic melanocytes. "This list included several oncogenes, namely MIR544A, MIR146B, FAM83A (also known as tumor antigen BJ‐TSA‐9), the cancer‐germline genes PBK (PDZ binding kinase) and PRAME (preferentially expressed antigen in melanoma), and GCKR that, with PRAME, is a downstream target of the BCR‐ABL protein." (PMID 29575763, 2018).
prostate carcinoma (1 paper, 2022). A carcinoma that arises from epithelial cells of the prostate gland. "MIR146B is considered as a tumor-suppressing factor, which inhibits proliferation and invasion of prostate cancer cells, and induces apoptosis." (PMID 35317831, 2022). "However, a recent report has revealed the tumor-promoting role of MIR146B and its upregulation in prostate cancer, demonstrating a double-edged sword role of this miRNA." (PMID 35317831, 2022).
tumor (2 papers, 2018 to 2022). "Increased expression levels of MIR146B were related with advanced stage, tumor size, extrathyroidal extension, and BRAF mutation, as previously reported." (PMID 30454026, 2018). "Taken together, these findings give evidences of the regulatory role of MIR146B in different tumor types, being able to act as tumor suppressor or oncomiR, depending on the context of altered regulatory pathways in each tumor type." (PMID 30454026, 2018).
immune dysfunction (1 paper, 2021). "Identification of Mir146b as a potential regulator of macrophage aging provides novel insights into immune dysfunction associated with aging." (PMID 34423778, 2021).
MIR146B also shares sentences with these, for which no sentence is quoted: cancer (2 papers); breast carcinoma (1); glioblastoma multiforme (1); glioma (1); Obesity (1); T-cell acute lymphoblastic leukemia (1).